PRMT5 (protein arginine methyltransferase 5)
Diseases named in the same sentence as PRMT5 in open-access papers (continued):
Sharing a sentence is not in itself a finding about the gene and the disease.
gastric cancer (27 papers, 2009 to 2026). A primary or metastatic malignant neoplasm involving the stomach. "Conversely, PRMT5 deficiency in a gastric cancer mouse model increases Lgr5+ stem cells and activates Wnt/β-catenin, indicating tumor-type specific roles." (PMID 41204384, 2025). "Gastric cancer caused by PRMT5 loss exhibited the increase in Lgr5+ stem cells, which are proposed to contribute to both the gastric tumorigenesis and progression in mouse models." (PMID 35864961, 2022). "Statistical analysis showed that low PRMT5 expression is associated with gastric cancer (n = 94, P < 0.01)." (PMID 35864961, 2022). "We propose that in these gastric cancer samples, low level of PRMT5 caused by gene deletion leads to or contributes to gastric tumorigenesis." (PMID 35864961, 2022). "Endogenous c-Myc was co-precipitated with Flag-PRMT5, implying an association between PRMT5 and c-Myc in gastric cancer cells." (PMID 32292506, 2020). "Furthermore, we discovered that the decreased PRMT5 expression was linked to a poor outcome for gastric cancer (n = 631, P < 0.001)." (PMID 35864961, 2022). "Furthermore, gland structure in antral tumors, together with the ectopic expression of CDX1, CDX2 and Villin, the well-known intestinal epithelial markers, suggested that gastric cancer caused by Prmt5 deletion was intestinal-type gastric cancer." (PMID 35864961, 2022). "All Prmt5-deficient mice displayed intestinal-type gastric cancer within 4 months of age." (PMID 35864961, 2022). "In gastric cancer, PRMT5-mediated H4R3me2s overlaps with c-Myc binding regions to silence genes such as PTEN, CDKN2C, and CDKN1A." (PMID 41204384, 2025). "PRMT5 promotes gastric cancer progression by recruiting DNMT3A to the promoter region of the tumor suppressor gene IRX1, enhancing its DNA methylation and silencing its expression." (PMID 41204384, 2025). "In parallel, we examined PRMT5 protein level in a human tissue microarray representing 94 patients with intestinal-type gastric cancer and adjacent normal tissues." (PMID 35864961, 2022). "We analyzed the alterations of PRMT5 gene in 434 human primary gastric cancer samples from TCGA database 20-23." (PMID 35864961, 2022). "Consistent with the notion that Lgr5 is the target of Wnt/β-catenin signaling, whose activation is the most predominant driver for gastric tumorigenesis, Prmt5 mutant gastric cancer showed the activation of Wnt/β-Catenin signaling." (PMID 35864961, 2022). "Taken together, Prmt5 deletion-induced gastric cancer exhibited the hyperactivation of Wnt/β-catenin signaling, recapitulating the molecular alterations in human gastric cancer." (PMID 35864961, 2022). "This seems to be contrary to the notion that PRMT5 can promote tumor growth and progression in a variety of human cancer cells including gastric cancers 11, 13-19." (PMID 35864961, 2022). "We found that 40.4% (38/94) of paired samples showed a lower expression of PRMT5 in the gastric cancer compared to the adjacent normal tissues." (PMID 35864961, 2022). "Previous studies have demonstrated the in vitro oncogenic role of protein arginine methyltransferase 5 (PRMT5) in gastric cancer cell lines." (PMID 35864961, 2022). "Of note, 20% (2/10) of Prmt5 mutants finally developed into invasive gastric cancer by 8 months of age." (PMID 35864961, 2022). "In particular, 20% (2/10) of Prmt5 mutant mice developed invasive gastric cancer that invaded into submucosa layer, as evidenced by H&E and the expression of E-cadherin." (PMID 35864961, 2022). "In fact, we also found that knockdown of PRMT5 in some gastric cancer lines with high level of PRMT5 did inhibit tumor growth." (PMID 35864961, 2022). "It is widely-recognized that PRMT5 can promote the proliferation, invasion, and migration of various human cancer cells, including gastric cancers 13-16, breast cancers 17, colorectal cancers 18, and lung cancers." (PMID 35864961, 2022).
gastric cancer (continued). "Herein, we provide the first critical in vivo role of PRMT5 in suppressing gastric cancer formation." (PMID 35864961, 2022). "By contrast, all Prmt5 mutant mice exhibited multistage process of the antral tumorigenesis, with hyperplasia at 2 months, microadenoma at 4 months, and gastric cancer at the age of 8 months." (PMID 35864961, 2022). "PRMT5, a histone arginine methyltransferase, is highly expressed in a wide range of malignant carcinomas, including ovarian, lung, and gastric cancers." (PMID 35884488, 2022). "In gastric cancer, miR-1304-5p participates in the circ-PRMT5/miR-145/miR-1304/MYC axis to promote tumor progression and the MYC gene is also associated with ‘double hit’ DLBCL, which indicates an unfavorable prognosis." (PMID 34109978, 2021). "Circ-PRMT5 contributed to gastric cancer development through up-regulating MYC via sponging miR-145 and miR-1304." (PMID 33892646, 2021). "Our results thus unravel novel mechanisms of c-Myc-mediated transcriptional repression and of PRMT5 recruitment and function within the context of gastric cancer, revealing a new potential strategy for targeted therapy." (PMID 32292506, 2020). "PRMT5-mediated GLI1 stabilization machinery has also been observed in the previously identified SHH-expressing gastric cancer cell line AGS and the small-cell lung cancer (SCLC) cell line H146." (PMID 32859041, 2020). "Specifically, we found that PRMT5 was required to promote gastric cancer cell growth in vitro and in vivo, and for transcriptional repression of this cohort of genes, which was dependent on its methyltransferase activity." (PMID 32292506, 2020). "This study aimed to clarify the role of PRMT5 in the transcriptional repression of c-Myc target genes in gastric cancer." (PMID 32292506, 2020). "The summarized IHC data indicated that PRMT5 expression was significantly upregulated in gastric cancer tissues compared with matched adjacent normal tissues." (PMID 32292506, 2020). "Collectively, we unraveled a novel mechanism by which PRMT5-dependent transcriptional repression of c-Myc target genes is required for gastric cancer progression." (PMID 32292506, 2020). "Nevertheless, our findings reveal important insights that link PRMT5-dependent transcription repression of c-Myc target genes and gastric cancer progression." (PMID 32292506, 2020). "Together, our results demonstrate that PRMT5 is important for gastric cancer cell growth potentially involving PTEN, p18, p21, p57 or p63 gene repression." (PMID 32292506, 2020). "Our current study revealed that cell cycle negative regulators p18, p21, p57, and tumor repressors PTEN and p63 are epigenetic targets of PRMT5 in gastric cancer." (PMID 32292506, 2020). "In order to identify potential transcriptional targets of PRMT5 in gastric cancer, a comprehensive analysis was performed by utilizing a quantitative RT-PCR array to profile the targets of PRMT5 in BGC823 and SGC7901 cells." (PMID 32292506, 2020). "Why PRMT5 is preferentially localized in the nucleus of gastric cancer cells remains to be explained." (PMID 32292506, 2020). "It is interesting that we observed a dominant nuclear localization of PRMT5 in both gastric cancer tissues and cells, although a small fraction was distributed in the cytoplasm as well." (PMID 32292506, 2020). "Large-scale cohort studies and detailed ChIP-seq analysis of PRMT5- mediated H4R3me2s and other histone marks would facilitate understanding their roles in transcriptional repression and gastric cancer progression." (PMID 32292506, 2020). "Our study demonstrated that PRMT5-dependent epigenetic repression of c-Myc target genes regulates gastric cancer progression." (PMID 32292506, 2020). "Our results are consistent with the observation by Kanda and coworkers in which PRMT5 was positively correlated with poor survival in gastric cancer." (PMID 32292506, 2020).
gastric cancer (continued). "To test this, we first performed immunofluorescence microscopy and observed co-localization of PRMT5 and c-Myc in gastric cancer BGC823 and SGC7901 cells." (PMID 32292506, 2020). "In the present study, we provide evidence of a direct and functional link between PRMT5-mediated H4R3me2s and c-Myc in gastric cancer." (PMID 32292506, 2020). "Both c-Myc and PRMT5 expression levels were upregulated in primary human gastric cancer tissues, and their expression levels inversely correlated with clinical outcomes." (PMID 32292506, 2020). "Based on this PRMT5 expression analysis in gastric cancer samples, we reasoned that depleting PRMT5 would attenuate the malignancy of gastric cancer cells." (PMID 32292506, 2020). "To understand the effects of MEP50/PRMT5 in HH-expressing cancer cells, we analysed the role of MEP50/PRMT5 in previously identified SHH-expressing gastric cancer cell line AGS14 and small cell lung cancer cell line H14617." (PMID 30675521, 2019). "Furthermore, in human gastric cancer samples, PRMT5 deletion and downregulation were frequently observed and associated with the poor prognosis." (PMID 35864961, 2022). "We also found that PRMT5 upregulation in 17% (16/94) gastric cancer samples." (PMID 35864961, 2022). "PRMT5 gene deletion was found in approximately 25% of human gastric cancer samples." (PMID 35864961, 2022). "Again, given the opposite roles of PRMT5 in the tumorigenesis and progression at least in gastric cancer, PRMT5 may regulate different downstream effectors to inhibit or activate Wnt/β-catenin signaling in different context." (PMID 35864961, 2022). "We next investigated whether Wnt/β-catenin signaling was hyperactivated in Prmt5 deletion-induced gastric cancer." (PMID 35864961, 2022). "circ-PRMT5 is reported to aggravate gastric cancer development by absorbing miR-145 and miR-1304." (PMID 34722753, 2021). "In these experiments, PRMT5 and c-Myc were upregulated in human gastric cancer tissues." (PMID 33440687, 2021). "Therefore, we designed three specific siRNAs targeting PRMT5, and their efficacy was verified by Western blot analysis in gastric cancer cells BGC823 and SGC7901." (PMID 32292506, 2020). "Notably, levels of PTEN (r = -0.4253, P < 0.01) or p57 (r = -0.4297, P < 0.01) exhibited a significant inverse correlation with PRMT5 levels in these gastric cancer samples calculated by Pearson correlation." (PMID 32292506, 2020). "Furthermore, PRMT5 knock down in gastric cancer cell lines results in attenuated cell growth and reduced metastasis." (PMID 30613353, 2018). "Therefore, like TGF-β signaling 60, PRMT5 may exert the opposite roles in the tumorigenesis and progression at least in gastric cancer." (PMID 35864961, 2022). "Therefore, it remained unexplored that what role PRMT5 plays in gastric cancer formation in vivo." (PMID 35864961, 2022). "This indicated that PRMT5 may act as a tumor suppressor in gastric cancer." (PMID 35864961, 2022). "Given our ongoing research on the role of arginine methylation in gastric cancer, we analyzed the expression of PRMT1 and PRMT5 in gastric cancer patients and found that their high expression was associated with poor prognosis." (PMID 40393971, 2025). "Our previous studies have shown that PRMT1 and PRMT4/CARM1 promote gastric cancer proliferation and metastasis, underscoring the significance of NUSAP1 interactions with PRMT1 and PRMT5." (PMID 40393971, 2025). "PRMT5 also interacts with c-MYC, which in turn is critical for H4R3me2s in repressing target genes to promote gastric cancer progression." (PMID 35655230, 2022). "To investigate the role of PRMT5 in gastric cancer, we first examined PRMT5 expression by immunohistochemistry using tissue arrays containing 90 pairs of gastric cancer and their matched non-tumorous tissues." (PMID 32292506, 2020).
gastric cancer (continued). "In this study, we found that c-Myc could interact directly with PRMT5 to transcriptionally repress the expression of a cohort of genes, including PTEN, CDKN2C (p18INK4C), CDKN1A (p21CIP1/WAF1), CDKN1C (p57KIP2) and p63, to promote gastric cancer cell growth." (PMID 32292506, 2020). "In a more recent study, PRMT5 has been shown to be overexpressed in a large cohort of human gastric tumors and to contribute to increased recruitment of DNA methyltransferase 3A (DNMT3A) to the promoter region of the tumor suppressor gene, Iroquois homeobox 1 (IRX1), in gastric cancer cells." (PMID 30613353, 2018).
lung adenocarcinoma (23 papers, 2016 to 2025). A carcinoma that arises from the lung and is characterized by the presence of malignant glandular epithelial cells. "PRMT5 expression level and copy number were correlated, with higher PRMT5 expression being associated with worse overall survival in lung adenocarcinoma patients." (PMID 38760429, 2024). "The PRMT5 inhibitor arginine methyltransferase inhibitor 1 (AMI‐1) caused cell‐cycle arrest in lung adenocarcinoma cells, which was more pronounced when combined with cisplatin." (PMID 35747993, 2023). "Bioinformatic analyses identified apoptosis, DNA damage, and cell cycle progression as the main PRMT5-associated functional pathways, and survival analysis linked the increased PRMT5 gene expression to worse overall survival in lung adenocarcinoma." (PMID 34200178, 2021). "Consistent with previous research in lung adenocarcinoma, we found knockdown PRMT5 attenuated the activity of SREBP1 in Tu686 cells." (PMID 36878903, 2023). "Protein arginine methyltransferase 5 (PRMT5), highly expressed in lung adenocarcinoma, was identified to be involved in tumorigenesis." (PMID 34200178, 2021). "PRMT5 was overexpressed in human lung adenocarcinoma cell lines compared with normal human foetal lung fibroblast cells (IMR90)." (PMID 30461193, 2019). "In contrast, cytoplasmic PRMT5 expression was recently shown to be directly correlated with poor prognosis in lung adenocarcinoma." (PMID 28107179, 2017). "In searching for molecules that mediate PRMT5/p44 functions in cell growth, we performed DNA microarray analysis with lung adenocarcinoma A549 cells expressing PRMT5 or p44 shRNA and identified a set of genes targeted by both PRMT5 and p44." (PMID 27480244, 2016). "Furthermore, we identified 27 ion channel (IC) genes exhibited a correlation with PRMT5 in lung adenocarcinoma (LUAD), of which 9 genes were identified as statistically significant with KM survival analysis." (PMID 39678513, 2024). "This study showed that treatment of A549 lung adenocarcinoma cells with a specific PRMT5 inhibitor, GSK591, suppressed the expression of TGF-β1-induced EMT protein markers such as Snail and Vimentin, treatment of T1-44 alone did not suppress the expression of PRMT5." (PMID 36765032, 2023). "Similar to the observations regarding alterations in SHARPIN expression in cancer, the expression level of PRMT5 was also found to be dramatically elevated in both human lung adenocarcinoma and squamous cell carcinoma compared with that in normal lung samples by analysis of RNA-sequencing from TCGA." (PMID 28903384, 2017). "In patients with lung adenocarcinoma (LUAD) and lung squamous cell carcinoma (LUSC), EP300-AS1 expression is negatively correlated with PRMT5 expression." (PMID 40790019, 2025). "The current study shows a novel selective antitumor activity of the epigenetic modifier, PRMT5 inhibitor AMI-1, additive to cisplatin in lung adenocarcinoma cells." (PMID 34200178, 2021). "In the current study, we examined the potential antineoplastic activity of PRMT5 inhibitor, arginine methyltransferase inhibitor 1 (AMI-1), and cisplatin on lung adenocarcinoma." (PMID 34200178, 2021). "In addition, we tested the mRNA level changes of PRMT5 and FXR1 in The Cancer Genome Atlas (TCGA) HNSCC and lung adenocarcinoma data sets." (PMID 38709899, 2024). "Hence, targeting PRMT5 to modulate FXR1 functions is significant and may provide a unique anti-tumor response for HNSCC and lung adenocarcinoma patients." (PMID 38709899, 2024). "To further address the clinical relevance of this hypothesis, we first utilized our proteomic and transcriptomic data from a prospectively collected lung adenocarcinoma cohort of Taiwan Cancer Moonshot to examine the correlation between MTAP/vimentin and PRMT5/vimentin." (PMID 35766227, 2022).
lung adenocarcinoma (continued). "Fourth, PRMT5 directly co-localized and interacted with AKT, albeit not with PTEN and mTOR; Akt phosphorylation at Thr308 and Ser473 and the downstream target GSK3 at Ser9 was markedly decreased without altering PTEN and mTOR phosphorylation at Ser2442 in PRMT5-deficient lung adenocarcinoma cells." (PMID 35493527, 2022).